EPCAM (epithelial cell adhesion molecule)
Diseases named in the same sentence as EPCAM in open-access papers (continued):
Sharing a sentence is not in itself a finding about the gene and the disease.
tumor (continued). "Also, EpCAM plays an important role in the suppression of anti-tumor immunity." (PMID 35986321, 2022). "Furthermore, IL-15 production by CD24+CD29+EpCAM+ epithelial cells was higher in PyMT tumors than in normal tissue and the deletion of tumor-expressed IL-15 resulted in a decrease of ILC1s, a downregulation of granzyme B and C expression, and a reduced tumor control." (PMID 36115839, 2022). "CDP0857 treatment significantly reduced the tumor size and volume of D-K-Ras MT cells harboring these mutations, and tumors excised from xenograft mice showed a significantly reduced expression of CD44, CD133 and EpCAM and of active forms of factors in the Wnt/β-catenin and Ras/ERK pathways." (PMID 35453609, 2022). "To analyze whether probe H5 could detect ongoing GzmB-mediated killing of tumor cells, we treated all samples with probe H5 (30 min, r.t.)and surface markers for epithelial cells (EpCAM), leukocytes (CD45), and cytotoxic T lymphocytes (CD8) before flow cytometry analysis." (PMID 35501326, 2022). "Therefore, EpCAM has been considered as a promising target for tumor diagnosis and therapy." (PMID 36546899, 2022). "However, tumor cells exhibit phenotypic heterogeneity with differential expression of EpCAM according to tumor origin and stage [epithelial to mesenchymal (EMT) phenotype] and may even be absent during EMT and in non-epithelial tumors." (PMID 36551601, 2022). "Furthermore, downregulation of EpCAM in CTCs that underwent epithelial–mesenchymal transition (EMT) may result in missing critical tumor cell subpopulations." (PMID 35681601, 2022). "However, several types of tumor cells express low level of EpCAM, and some CTCs may lose the expression of EpCAM during the process of EMT." (PMID 36091119, 2022). "However, it has been revealed that EpCAM could be a tumor suppressive protein in certain types of cancers." (PMID 35975801, 2022). "In addition, the effect of tumor microenvironment on tumor cell EpCAM expression was investigated." (PMID 36077658, 2022). "It is speculated that EpCAM’s prognostic value depends on the tumor entity." (PMID 34453639, 2021). "It has been demonstrated that ascitic fluid from ovarian cancer patients contains EVs which may promote tumor cell migration necessary in metastasis by transferring molecules such as CD24 and EpCAM to recipient cells which are associated with increased tumor invasiveness." (PMID 34572444, 2021). "Additionally, the decreased protein level of EpCAM was confirmed in mouse xenografted tumor tissues derived from SiHa-Slug cells (the xenografted tumor tissues were collected in our previous study) by western blot (p < 0.05) and immunohistochemistry (p < 0.05)." (PMID 33691694, 2021). "In addition, LDN‐212854 inhibited ID1 and EpCAM expression in tumor tissue specimens." (PMID 33834612, 2021). "The expression of EpCAM in tumor cells could maximize the robustness of the RhoA cycle during its transit through the fast recycling endosomal pathway, thus ensuring that tensile forces are correctly generated at the cell scale and therefore supporting tumor propagation." (PMID 33850145, 2021). "Therefore, we used EpCAM expression as a marker for EVs secreted by tumor cells." (PMID 34439276, 2021). "Besides, this expression often closely correlates with the epithelial–mesenchymal transition (EMT)-regulating tumor invasion and metastasis: the tumor cells have been observed to undergo loss of EpCAM expression during EMT and release a large number of EpCAM-enriched EVs simultaneously." (PMID 34900726, 2021).
tumor (continued). "Thus utility of EpCAM as the CTC capture agent may in part demonstrate the progression of tumor and possible de-differentiation which carries significance especially during the course of treatment." (PMID 34600526, 2021). "Furthermore, neoplastic cells from pediatric carcinomas could also be clearly distinguished from other hematopoietic and non-hematopoietic neoplastic cells based on their stronger expression of EpCAM compared with all other tumor subtypes." (PMID 34638431, 2021). "On the other hand, researchers found that catumaxomab as adjuvant therapy could induce T cell activation and migration to peripheral tissues against gastric cancer, consequently leading to secondary antitumor immune responses to various tumor antigens other than EpCAM." (PMID 34832954, 2021). "In normal conditions, EpCAM is involved in cell–cell adhesion and regulates the differentiation in progenitor and embryonic stem cells; however, in the context of cancer, its overexpression is related to increased cell proliferation, migration, invasion and tumour metastasis." (PMID 34769211, 2021). "Moreover, high EpCAM expression was associated with positive AFP expression (P = 0.042), vascular invasion rate (P = 0.043), poor tumor differentiation (P = 0.020), and advanced tumor–node–metastasis stage (P = 0.002)." (PMID 31740785, 2020). "Given that EMT and EndoMT are substantially involved in tumor neovascularization and that the mesenchymal molecule Vimentin is regarded as an independent prognosticator for poor survival, it is ideal to integrate Vimentin and/or EpCAM into the iFISH co-detection platform." (PMID 32599893, 2020). "However, EpCAM’s prognostic value varies depending on the tumor entity." (PMID 32507912, 2020). "The EpCAM expression on the surfaces of the leukocyte could emanate from (a) the activation of originally silent molecular pathways, (b) the uptake of tumor-derived extracellular vesicles by cell–EV membrane fusion, or (c) the internalization and expression of functional EpCAM mRNA by leukocytes." (PMID 33333805, 2020). "Similarly, tumor weights were significantly higher in the EpCAM+ group (4.56 ± 0.42 g, p < 0.001), followed by the mixed group with 50% EpCAM+ CSCs (2.77 ± 0.69 g), and least in the EpCAM- group with 0% CSCs, (0.8 ± 0.50 g)." (PMID 32547703, 2020). "Therefore, antibodies against EpCAM cannot detect all tumor subtypes." (PMID 32823926, 2020). "However, EpCAM is known to be highly expressed on the tumour types of epithelial origin." (PMID 32046162, 2020). "However, it is also possible that under some conditions, stimulation of motility may dominate over cell–cell adhesion, in which case EpCAM might help single cells to escape from the tumour." (PMID 32961790, 2020). "Taking into account that tumor-derived exosomes are diluted in the bloodstream with a large number of vesicles secreted by healthy tissue, researchers have identified proteins such as EpCAM that were reported to be more selectively expressed on tumor-associated vesicles of PDAC cells." (PMID 31941049, 2020). "The EpCAM-High group of animals showed significantly higher tumor volume (2451.25 ± 443.34 mm3, p = 0.013, n = 4 mice/group) and significantly higher liver weight (4.375 ± 0.7 g, p = 0.023, n = 4 mice/group) compared to the EpCAM-Low group (tumor volume: 282.22 ± 282 mm3, liver weight:1.7 ± 0.1 g)." (PMID 32547703, 2020). "However, EpCAM might be a key molecule for CTC colonization, and metastatic tumor formation, at least for most of the cancer types in which EpCAM+ CTCs are abundant." (PMID 32764280, 2020). "Importantly, the EpCAM+/CSV− CTCs exhibited significantly lower viability than unsorted tumor cells, suggesting that epithelial phenotype may reduce the survival ability of CTCs in shear flow." (PMID 33143160, 2020).
tumor (continued). "Based upon the EpCAM-score of the groups [(i) negative (E−/−), (ii) heterogeneous (E−/+), (iii) homogeneous (E+/+)], we were interested in the outcome of the patients in order to understand whether EpCAM-expression determined a tumor subgroup characterized by poor prognosis." (PMID 33225916, 2020). "Indeed, the DRP markers such as Prom1, EpCAM, Krt19, and Sox9 detected in AH, were also induced in non-tumor liver tissue (NTL) of mice subjected to DEN injection and tumor promotion with WAD as compared to normal liver or tumor tissues, suggesting a more selective increase of DRPs in NTL." (PMID 33173221, 2020). "Thus, the LuM1-derived oncosomes could contain MMP3 and CD326/EpCAM, whose transfer may induce stemness in recipient cells in the local tumor microenvironment and distant organs." (PMID 32260433, 2020). "If it is possible to show that primary surgery followed by postoperative radiotherapy is more effective than primary radiation therapy for HNSCC expressing EpCAM intensively, a more individualized treatment approach could be offered to patients according to their specific tumor characteristics." (PMID 31361893, 2019). "Moreover, we could also establish a HOV26T sarcomatous cell line, which was probably EpCAM-nagative, from the sarcomatous component in the original tumor." (PMID 31248002, 2019). "Moreover, EpCAM and CD133 are expressed by microparticles, AnnexinV+ EpCAM+ CD147+ and AnnexinV+ EpCAM+ ASGPR1+ CD133+ tumor-associated microparticles (taMPs), in CCA liquid biopsy and have been proved to be a significant non-invasive diagnostic and prognostic tool." (PMID 31450710, 2019). "CTC separation and counting focusing only on positive EpCAM could be one-sided, which could lead to a large amount of tumor cells with other positive markers (such as EGFR positive cells, EMT inverted cells) being ignored, and the sensitivity could be low as well." (PMID 31767014, 2019). "Unlike flow cytometry, fluorescence microscopy and microfluidic chips, the detection of tumor cells can be carried out on the electrode surface and maybe further used for CTC detection since the identification of CTCs usually relies on the presence of EpCAM on tumor cell membranes." (PMID 31010258, 2019). "Moreover, higher nuclear SHCBP1 was detected in NSCLC cells cultured in serum-free medium than in serum-containing medium, as well as in CD44/ EpCAM double-positive cells compared to the corresponding parental tumor cells, suggesting an important role of nuclear SHCBP1 in CSCs regulation." (PMID 30177836, 2019). "One explanation for this discrepancy may be that traditional immunocytochemistry methods only measure epithelial antigens such as cytokeratin and EpCAM, which can be frequently downregulated in metastatic tumor cells or cells that revert to a ‘stem cell-like’ phenotype." (PMID 31432366, 2019). "At present, positive separation of circulating tumor cells (CTC) taking EpCAM as the marker was used in most cases which could be one-sided, while this study successfully prepared four antibody-modified magnetic immunoliposomes (MIL) by using the self-assembled liposome with antibody derivatives." (PMID 31767014, 2019). "However, EpCAM expression is transiently downregulated during EMT, which could argue for EpCAM prohibiting tumor cell dissemination." (PMID 31921628, 2019). "The double-positive feedback loop mediated by the Wnt and AKT/mTOR pathways, two critical signalling pathways in NPC cells, might be used to keep EpCAM at a high level and promote tumour progression, although further experiments are needed to verify this hypothesis." (PMID 29305578, 2018). "Furthermore, pulsing DCs with EpCAM peptides significantly suppressed tumor growth." (PMID 29298343, 2018).
tumor (continued). "Malignant pEMT cells were preferentially located at leading edges of tumor areas, and their signature was reciprocal to that of the epithelial differentiation, which was codefined by high expression of the pan-carcinoma epithelial cell adhesion molecule (EpCAM)." (PMID 30261040, 2018). "However, in some types of tumor cells, EpCAM expression is down-regulated and even in epithelial cancers, the expression level of EpCAM can be turned into weak- or negligible level after epithelial-mesenchymal transition (EMT), which is natural and inevitable pathway of tumor progression." (PMID 30315187, 2018). "Moreover, chronic inflammation, caused by HBV/HCV infection, also can increase stemness (EpCAM and CD13), which may be in favor of tumor recurrence." (PMID 28572700, 2017). "During the metastasis formation tumor cells are losing their cell-cell contact supposedly accompanied with a downregulation of E-Cadherin (ECad) and epithelial markers such as the epithelial cell adhesion molecule (EpCam), cytokeratin (CK), and an upregulation of Vimentin21." (PMID 28855609, 2017). "Finally, the discovery of CSCs has helped us to understand the molecular mechanism of tumour genesis and development, and improvements in our understanding of the biological effects of EpCAMwill hopefully help us to develop new effective anti-EpCAM strategies." (PMID 28403178, 2017). "Hence, EpCAM expression on primary tumor cells but also on CTCs might activate proliferation and tumor initiation at distant sites, and is a novel parameter, whose measurement might represent a surrogate for differing phenotypic states of cancer cells." (PMID 27683128, 2017). "As changes in protein expression could potentially occur during filtration, we also tested whether filtration of live tumor cells with our protocol induces a change in antigen expression by using EpCAM antibody immunofluorescence and labeling live MCF-7 cells before and after filtration." (PMID 28060956, 2017). "Furthermore, analysis of the tumors from the different population showed that in most cases CD49f+/EpCAM+/E-cadherinlow and CD49f+/EpCAM+/E-cadherinhigh cells were able to give rise to all populations in the tumor suggesting some plasticity between the two populations." (PMID 29162812, 2017). "Furthermore, in an in vivo mouse model, platinum agents preferentially eliminated EpCAM-negative cells in comparison with EpCAM-positive cells, suggesting that the remaining subpopulation of EpCAM-positive cells contributes to tumor recurrence after chemotherapy." (PMID 28574829, 2017). "Interestingly, two studies used CellSearch® system to detect CTCs before and after surgery, and found no statistical correlation between EpCAM (+) CTCs count and survival or recurrence, demonstrating EpCAM (−) CTCs or M-CTCs also should be evaluated to monitor tumor progression." (PMID 28423562, 2017). "However, EpCAM was not considered as a tumour stem cell marker because it appeared to be associated with a more favorable prognosis in other studies." (PMID 28403178, 2017). "Moreover, efforts to develop new strategies for CTCs isolation and characterisation, and the translation of CTCs into clinical practice needs to overcome the limitation associated with the sole use of Epithelial Cell Adhesion Molecule (EpCAM) expression to purify this tumour cell subpopulation." (PMID 27711186, 2016). "In addition, EpCAM positivity was confirmed in our series of samples showing strong immunostaining in well-differentiated tumour areas while positivity was moderate in poorly differentiated tumour areas." (PMID 27901069, 2016). "Magnetic beads coated with anti-EpCAM or anti-EGFR could isolate tumour cells with high efficiency." (PMID 27711186, 2016). "Importantly, EpCAM+CD147+ taMPs correlated with the measured tumour-volume in CRC patients." (PMID 27127176, 2016).
tumor (continued). "Epithelial cell adhesion molecule-positive (EpCAM+) CTCs are a proven independent risk factor for HCC recurrence in our previous study, while immune suppressive CD4+CD25+ regulatory T cells (Treg) intra-nuclear expressing Foxp3+ are associated with tumor immune tolerance and immune escape." (PMID 27439521, 2016). "In addition, we tested several markers involved in tumor invasion and migration, including epithelial cell adhesion molecule (EpCAM), αvβ6 integrin, urokinase-type plasminogen activator receptor (uPAR), and epithelial membrane antigen (EMA, also known as MUC1)." (PMID 26946151, 2016). "Since EpCAM knockdown and EpAb2-6 treatment disrupted cancer cell growth and induced cancer cell apoptosis in vitro, we investigated whether EpAb2-6 could be used to directly inhibit tumor growth in vivo." (PMID 26317650, 2015). "However, down-regulation or loss of both EpCAM and CK were reported in EMT CTC, such inherited property of tumor cell may result in failure to detect significant amount of CTCs by the conventional strategy." (PMID 25909226, 2015). "CTC enrichment methods can broadly be divided into EpCAM-dependent cell selection that allows the identification of epithelial tumor cells and on the other hand the EpCAM-independent cell selection methods that may help to identify additional mesenchymal-like CTC subpopulations." (PMID 25398926, 2015). "Therefore, the generation of inhibitors or antibodies against EpCAM may facilitate the development of tumor-targeting therapy." (PMID 26317650, 2015). "Moreover, our finding of circulating cells with positive vimentin expression supports the contention that EpCAM-based CTC isolation may underestimate the number of neoplastic elements likely delivered from primitive tumor to the blood stream." (PMID 26571236, 2015). "Finally, the tumor lysate was extracted from purified CD45−/EpCAM+ tumor cells." (PMID 26702369, 2015). "In addition, emerging evidence suggests that EpCAM may be a critical factor in tumor development, progression, and metastasis." (PMID 26356670, 2015). "However, considering the association between EpCAM+ cells and PC3 cell proliferation and metastasis, targeting this small population of cells may cause dramatic tumor-killing effects." (PMID 25636521, 2015). "Thus we were able to elucidate the EpCAM down regulation mediated anti-tumor effect of EpApt-siEp." (PMID 26176230, 2015). "On the other hand, tumor cells that have transformed to a more mesenchymal-like phenotype, and thus exhibit greater plasticity, may prove to be less easily detected by conventional EpCAM-based detection methods." (PMID 25398926, 2015). "Furthermore, high EpCAM expression correlates with tumor grading and the prognosis of the tumors." (PMID 24727741, 2014). "The presence of CD133+EpCAM+ cells in the normal tissue and their higher number in the tumor suggest that cells of such phenotype are important for the development of cancer and these particular cells may be the target of carcinogenesis, but this hypothesis needs further research." (PMID 23959111, 2014). "The prevalence of the full length EpCAM and Ep-ICD in a variety of human cancers has been recently reported using tissue microarrays suggesting loss of membranous EpEx is a common event in human epithelial cancers and the ratio of EpEx and Ep-ICD is dependent on the tumor." (PMID 25265904, 2014). "In addition, EPCAM has recently been identified to be a surface biomarker of cancer stem cells (CSCs), which refer to a subset of phenotypically distinct cells mainly responsible for tumor growth and heterogeneity maintenance." (PMID 24718422, 2014).